SLC16A11 (solute carrier family 16 member 11)
Description:
Proton-linked monocarboxylate transporter. It catalyzes the transport of pyruvate across the plasma membrane. Probably involved in hepatic lipid metabolism: overexpression results in an increase of triacylglycerol(TAG) levels, small increases in intracellular diacylglycerols and decreases in lysophosphatidylcholine, cholesterol ester and sphingomyelin lipids.
Synonyms: MCT 11; MCT11; FLJ90193
Gene: Protein-coding gene on chromosome 17 (7,041,621 to 7,044,092, reverse strand). Ensembl gene ENSG00000174326.
Subcellular location: Endoplasmic reticulum membrane; Cell membrane
Genetic constraint (gnomAD): Loss-of-function variants: 24 observed, 18.52 expected, observed/expected ratio (o/e) 1.3, 90% interval 0.94 to 1.78. The synonymous counts are far from expectation, so gnomAD's model fits this gene poorly and the ratio says little. Missense variants: 638 observed, 512.67 expected, observed/expected ratio (o/e) 1.24, 90% interval 1.16 to 1.33. Synonymous variants: 332 observed, 260.69 expected, observed/expected ratio (o/e) 1.27, 90% interval 1.16 to 1.39.
Homologues: Orthologues: chimpanzee SLC16A11 (99% identical), macaque SLC16A11 (97% identical), pig SLC16A11 (90% identical), rabbit SLC16A11 (88% identical), mouse Slc16a11 (87% identical), rat Slc16a11 (87% identical), dog SLC16A11 (87% identical), guinea pig SLC16A11 (87% identical), zebrafish si:dkey-246g23.4 (30% identical), zebrafish zgc:114041 (30% identical), Drosophila melanogaster Sln (29% identical), Caenorhabditis elegans mct-6 (27% identical), and 11 more. Paralogues in human: SLC16A13 (44% identical), SLC16A8 (35% identical), SLC16A7 (33% identical), SLC16A3 (31% identical), SLC16A12 (30% identical), SLC16A1 (29% identical), SLC16A5 (28% identical), SLC16A14 (27% identical), SLC16A10 (26% identical), SLC16A9 (26% identical), SLC16A4 (25% identical), SLC16A2 (24% identical), and 1 more.
Diseases named in the same sentence as SLC16A11 in open-access papers:
SLC16A11 is named in the same sentence as 15 diseases in open-access papers, as found by Europe PMC text mining. Sharing a sentence is not in itself a finding about the gene and the disease. The quoted sentences say what the papers report.
type 2 diabetes (11 papers, 2015 to 2025). "It was further reported that the interaction of SLC16A11 with BSG was dysregulated in Type 2 diabetes variants." (PMID 40355756, 2025). "A GWAS on genetic risk factors associated with type-2 diabetes across individuals from Mexico and Latin America identified a novel introgressed locus spanning SLC16A11 and SLC16A13 associated with type 2 diabetes." (PMID 36503519, 2022). "Furthermore, type II diabetes was associated with SLC16A11, SLC30A8, SLC39A11 and MTCH2." (PMID 40355757, 2025). "While all three sites of SLC16A6 function might be important determinants of height, the association of loss-of-function coding variations within the pyruvate transporter SLC16A11 gene and type 2 diabetes mellitus appears to be due to loss of SLC16A11 function in liver exclusively." (PMID 30692937, 2018). "Twenty-five of these were previously reported type 2 diabetes-associated variants, including those consistently identified in multiple populations (e.g. variants at KCNQ1 and TCF7L2) and others enriched in the Latino population (e.g. variants at SLC16A11)." (PMID 37148359, 2023). "Existing studies have confirmed that MCT11(SLC16A11) and MCT13(SLC16A13) are related to type 2 diabetes, and MCT12(SLC16A12) is involved in the development of juvenile cataracts." (PMID 34424811, 2021).
diabetes (9 papers, 2018 to 2025). "For instance, the SLC16A11 risk variants, more common in people of Mexican ancestry, are associated with increased diabetes risk." (PMID 40129663, 2025). "For SLC16A11, this gene is more likely related with human diabetes as single nucleotide polymorphism of SLC16A11 making genomic variants in different populations." (PMID 32355273, 2020). "The SLC16A11 sequence variants were significantly associated with risk for diabetes in the Mexican origin group (P = 0.025), replicating the SIGMA findings." (PMID 30696834, 2019). "The previously reported effects of SLC16A11 variants on diabetes in Mexican samples was replicated in a large Mexican-American sample, but these effects were not significant in five non-Mexican Hispanic/Latino groups sampled from U.S. populations." (PMID 30696834, 2019). "For individuals harboring pathogenic variants in SLC16A11, the resulting consequences in lipid metabolism may drive their likelihood of developing diabetes much more so than any effect MAP3K15 may have on glucose uptake or gluconeogenesis." (PMID 36383675, 2022). "SLC16A11 might have a role in hepatic lipid metabolism and its genetic variation might result in diabetes risk." (PMID 31816988, 2019). "Five sequence variants in SLC16A11 (rs117767867, rs13342692, rs13342232, rs75418188, and rs75493593), which occur in two non-reference haplotypes, were recently shown to be associated with diabetes in Mexicans from the SIGMA consortium." (PMID 30696834, 2019). "While PTVs in MAP3K15 seem to associate with protection from diabetes broadly, a notable exception was in Admixed American individuals in MCPS who carried the well-known SLC16A11 risk haplotype." (PMID 36383675, 2022). "The associations of SLC30A8 and SLC16A11 with diabetes are well-described, but the disease mechanisms have not been fully elucidated yet and accordingly ClinVar and Orphanet do not report this association." (PMID 40355757, 2025). "In a meta-analysis of all groups, the association of SLC16A11 variants with diabetes was not significant (p = 0.27)." (PMID 30696834, 2019).
Insulin resistance (3 papers, 2021 to 2025). Increased resistance towards insulin, that is, diminished effectiveness of insulin in reducing blood glucose levels. "The differential effect on peripheral insulin resistance between men and women appears to be associated with the SLC16A11 and PPP1R3A genes, since the effect size of the SNPs of these genes was much larger in women." (PMID 37291636, 2023). "Only the reincorporation of the mutated SLC16A11 gene into the knockout rendered a mouse that developed excessive lipid accumulation and insulin resistance when fed a high fat diet." (PMID 33909378, 2021). "SLC16A11 (rs13342692, intronic) influences hepatic lipid handling supporting a role in lipid metabolism and hepatic insulin resistance in later-onset T2D." (PMID 40677239, 2025).
Obesity (3 papers, 2010 to 2021). Accumulation of substantial excess body fat. "Nonetheless, a positive association between SLC16A11 risk genotypes with BMI and insulin was found in nondiabetic individuals, which indicates that the SNP can be considered an early risk marker for obesity and T2D." (PMID 33909378, 2021). "Furthermore, also Slc16a11 expression differs under distinct dietary conditions and food deprivation, pointing towards distinct roles of these SLC16 transporters in diet-induced obesity." (PMID 34211098, 2021). "Other module genes related to lipid metabolism and obesity include Anxa5 (annexin A5), Ccna2 (cyclin A2), Ces5 (carboxylesterase 5), Cyp2c38 (cytochrome P450, family 2, subfamily c, polypeptide 38), Setd8 (SET domain containing 8), and Slc16a11 (monocarboxylic acid transporters, member 11)." (PMID 21179437, 2010).
pancreatic cancer (2 papers, 2020 to 2024). "However, SLC16A11 and SLC16A13 are acting as favor prognosis genes for pancreatic cancer if higher than median expression in TCGA cohort." (PMID 32355273, 2020).
liver cancer (1 paper, 2024). An epithelial or non-epithelial malignant neoplasm that arises from the liver. "Among these, six genes were significantly differentially expressed between liver cancer tissue and adjacent normal tissue (CSAD, SLC16A11, LILRA2, IMMP2L, GLP2R, and DHDH)." (PMID 38927691, 2024).
tumor (8 papers, 2021 to 2025). "A majority of the previously unpublished genes have been associated with tumorigeneses and tumor-suppressor pathways, primarily in cancer phenotypes, including: SLC16A11, POLR2A, C11orf87, and SLC12A747–52." (PMID 40050615, 2025). "Here, we show that tumor-infiltrating Tex cells highly upregulate the Slc16 monocarboxylate transporter (MCT) Slc16a11 (MCT11), enabling increased uptake of monocarboxylates (such as lactic acid) upon tumor infiltration." (PMID 39516648, 2024). "In hypoxic tumor environments, exhausted T cells markedly upregulate the lactate transporter SLC16A11 (MCT11), leading to increased lactate uptake." (PMID 41152975, 2025). "In the tumor microenvironment, CD8+ T cells have been shown to be functionally exhausted with impaired proliferation, secretion of inflammatory cytokines, and expression of markers such as PD-1, Tim3, Lag3, Slc16a11, CD49b, Tox, and others." (PMID 39320047, 2024).
cancer (4 papers, 2020 to 2025). A tumor composed of atypical neoplastic, often pleomorphic cells that invade other tissues. "However, studies on SLC16A4, SLC16A10, SLC16A11, SLC16A13, and SLC16A14 in cancer are still lacking." (PMID 34424811, 2021).
SLC16A11 also shares sentences with these, for which no sentence is quoted: melanoma (2 papers); adenocarcinoma (1); endometritis (1); head and neck squamous cell carcinoma (1); multiple myeloma (1); ovarian carcinoma (1); renal carcinoma (1).